ENSG00000225112 (novel transcript)
Gene: Long non-coding RNA gene on chromosome 10 (13,707,664 to 13,729,815, forward strand). Ensembl gene ENSG00000225112.
Gene Ontology:
Molecular function: structural constituent of ribosome
Cellular component: ribosome